TYMP (thymidine phosphorylase)
Description:
May have a role in maintaining the integrity of the blood vessels. Has growth promoting activity on endothelial cells, angiogenic activity in vivo and chemotactic activity on endothelial cells in vitro. Catalyzes the reversible phosphorolysis of thymidine. The produced molecules are then utilized as carbon and energy sources or in the rescue of pyrimidine bases for nucleotide synthesis.
Synonyms: TP; ECGF1; ECGF; MEDPS1; MNGIE; MTDPS1; PDECGF; hPD-ECGF
Tractability: Small molecule: an approved drug acts on it; a structure with a bound ligand is known; a high-quality ligand is known; it has a high-quality binding pocket; it belongs to a druggable protein family. PROTAC: its protein half-life has been measured; a small molecule that binds it is known.
Target class: Enzyme
Safety:
Unwanted effects reported when the protein is acted on. In parentheses: how it was acted on, where the effect was seen, and who reports it.
drug toxicity (source: ClinPGx)
drug toxicity and may require dose modification (source: ClinPGx)
Gene: Protein-coding gene on chromosome 22 (50,525,752 to 50,530,326, reverse strand). Ensembl gene ENSG00000025708.
Subcellular location (Human Protein Atlas): Golgi apparatus; Nuclear bodies; Cytosol
Pathways (Reactome):
Metabolism: Pyrimidine catabolism; Pyrimidine salvage
Gene Ontology:
Molecular function: protein binding; protein homodimerization activity; thymidine phosphorylase activity; 1,4-alpha-oligoglucan phosphorylase activity; glycosyltransferase activity; pentosyltransferase activity; pyrimidine-nucleoside phosphorylase activity
Biological process: pyrimidine nucleoside metabolic process; carbohydrate derivative metabolic process; dTMP catabolic process; nucleobase-containing small molecule metabolic process; pyrimidine nucleobase metabolic process; pyrimidine-containing compound metabolic process
Cellular component: cytosol
Genetic constraint (gnomAD): Loss-of-function variants: 49 observed, 40.95 expected, observed/expected ratio (o/e) 1.2, 90% interval 0.95 to 1.52. The synonymous counts are far from expectation, so gnomAD's model fits this gene poorly and the ratio says little. Missense variants: 837 observed, 605.46 expected, observed/expected ratio (o/e) 1.38, 90% interval 1.3 to 1.46. Synonymous variants: 363 observed, 282.41 expected, observed/expected ratio (o/e) 1.29, 90% interval 1.18 to 1.4.
Gene-disease validity (ClinGen):
ClinGen rates the evidence that TYMP causes each of these diseases.
mitochondrial disease (autosomal recessive): Definitive.
Homologues: Orthologues: chimpanzee TYMP (99% identical), guinea pig TYMP (80% identical), mouse Tymp (79% identical), rabbit TYMP (75% identical), rat Tymp (70% identical), tropical clawed frog tymp (52% identical), zebrafish tymp (19% identical).
Diseases named in the same sentence as TYMP in open-access papers:
TYMP is named in the same sentence as 147 diseases in open-access papers, as found by Europe PMC text mining. Sharing a sentence is not in itself a finding about the gene and the disease. The quoted sentences say what the papers report.
mitochondrial neurogastrointestinal encephalomyopathy (70 papers, 2011 to 2025). A syndrome characterized by the association of gastrointestinal dysmotility, peripheral neuropathy, chronic progressive external ophthalmoplegia and leukoencephalopathy. "Mitochondrial neurogastrointestinal encephalomyopathy (MNGIE) is caused by pathogenic mutations in the nuclear TYMP gene, which encodes the cytosolic enzyme thymidine phosphorylase." (PMID 41009664, 2025). "Mutations in thymidine phosphorylase cause excess accumulation of toxic metabolites and mitochondrial neurogastrointestinal encephalomyopathy (MNGIE) characterized by progressive deterioration of the GI tract." (PMID 40268053, 2025). "Mitochondrial neurogastrointestinal encephalomyopathy (MNGIE) is linked to heritable loss-of-function mutations in the gene encoding for thymidine phosphorylase (TYMP)." (PMID 40519286, 2025). "Inherited deficiency of thymidine phosphorylase (TP), encoded by TYMP, leads to a rare disease with multiple mitochondrial DNA (mtDNA) abnormalities, mitochondrial neurogastrointestinal encephalomyopathy (MNGIE)." (PMID 38741129, 2024). "Mutations in the TYMP gene can lead to MitochondrialNeurogastrointestinal Encephalopathy (MNGIE) syndrome, a rare genetic disorder." (PMID 38712004, 2024). "It has been shown that loss of TYMP leads to mitochondrial neurogastrointestinal encephalopathy and TYMP interacts with VEGF to promote the breakdown of the blood-brain barrier." (PMID 37100811, 2023). "Mitochondrial neurogastrointestinal encephalopathy is a rare multisystem autosomal recessive disease caused by mutations in the TYMP gene, that encodes for thymidine phosphorylase." (PMID 36192783, 2022). "Of note, mitochondrial neurogastrointestinal encephalopathy (MNGIE) is a well-described autosomal recessive condition resulting from mutations in the thymidine phosphorylase gene, leading to impaired intestinal motility and also involving other organs." (PMID 35482095, 2022). "Mitochondrial neurogastrointestinal encephalopathy (MNGIE) is an autosomal recessive disorder caused by mutations in the TYMP gene, which encodes for thymidine phosphorylase." (PMID 36192783, 2022). "Mutations in TYMP cause mitochondrial neurogastrointestinal encephalomyopathy (MNGIE), a recessive disorder characterized by gastrointestinal dismotility, cachexia, ptosis, progressive external ophtalmoplegia, peripheral neuropathy and leukoencephalopathy." (PMID 34208592, 2021). "Biallelic TYMP variants result in the mitochondrial neurogastrointestinal encephalomyopathy (MNGIE), a juvenile-onset disorder with progressive course and fatal outcome." (PMID 32849836, 2020). "Mitochondrial neurogastrointestinal encephalomyopathy (MNGIE) is an inherited disease caused by a deficiency in thymidine phosphorylase and characterized by elevated systemic deoxyribonucleotides and gastrointestinal (GI) and neurological manifestations." (PMID 33159497, 2020). "Mutations in human TYMP are associated with mitochondrial neurogastrointestinal encephalopathy (MNGIE), a disease characterized by mitochondrial DNA alterations leading to mitochondrial dysfunction." (PMID 33575564, 2020). "Mitochondrial neurogastrointestinal encephalomyopathy (MNGIE) is a rare autosomal metabolic disorder caused by thymidine phosphorylase (TP) deficiency." (PMID 32368563, 2020). "Mitochondrial neurogastrointestinal encephalomyopathy (MNGIE) is a fatal autosomal recessive disorder caused by mutations in TYMP, the gene that encodes for thymidine phosphorylase (EC 2.4.2.4)." (PMID 32183169, 2020). "We report a 19-year-old Cape Verdean woman with typical clinical features of MNGIE syndrome in whom we identified a novel homozygous TYMP gene mutation." (PMID 31885962, 2019). "Mitochondrial neurogastrointestinal encephalomyopathy (MNGIE) is an autosomal recessive disease characterized by deficiency of thymidine phosphorylase (TP)." (PMID 31709204, 2019).
mitochondrial neurogastrointestinal encephalomyopathy (continued). "Mitochondrial neurogastrointestinal encephalomyopathy (MNGIE) is a rare inherited metabolic disorder caused by loss-of-function mutations in the nuclear gene TYMP leading to thymidine (Thd) and deoxyuridine (d-Urd) accumulation." (PMID 30340467, 2018). "Mitochondrial neurogastrointestinal encephalopathy (MNGIE) syndrome is an mtDNA depletion syndrome caused by deficiency of thymidine phosphorylase, resulting in imbalances in mitochondrial nucleotide pools." (PMID 27504452, 2016). "Mitochondrial neurogastrointestinal encephalomyopathy (MNGIE) is a rare autosomal disease that is associated with a defect in TYMP, but is late in onset; mitochondrial mutations are associated with ophthalmoparesis aberrant behavior." (PMID 25923076, 2015). "Mitochondrial neurogastrointestinal encephalomyopathy (MNGIE) is a rare autosomal recessive mitochondrial disease associated with mutations in the nuclear TYMP gene." (PMID 24802030, 2014). "Mitochondrial neurogastrointestinal encephalomyopathy (MNGIE) is a rare autosomal recessive mitochondrial disease due to mutations in the nuclear TYMP gene encoding thymidine phosphorylase (TP)." (PMID 24802030, 2014). "Mutations in the fourth gene, TYMP (Entrez Gene ID 1890), encoding thymidine phosphorylase, cause mitochondrial neurogastrointestinal encephalomyopathy (MNGIE, OMIM ID #603041)." (PMID 21483760, 2011). "Mutations in the TYMP gene are linked to mitochondrial neurogastrointestinal encephalomyopathy." (PMID 40303404, 2025). "Mitochondrial neurogastrointestinal encephalomyopathy (MNGIE) is a very rare, devastating autosomal recessive mitochondrial disease caused by thymidine phosphorylase deficiency due to TYMP mutations, which usually leads to death in early adulthood." (PMID 41517394, 2025). "Mitochondrial neurogastrointestinal encephalomyopathy (MNGIE) is a rare, fatal, autosomal recessive disease associated with a deficiency in the thymidine phosphorylase (TP) enzyme, encoded by the TYMP gene." (PMID 38673463, 2024). "Mitochondrial neurogastrointestinal encephalomyopathy (MNGIE) is a rare autosomal recessive disease caused by pathogenic variants in the nuclear TYMP gene encoding the thymidine phosphorylase enzyme." (PMID 38978706, 2024). ", which encodes thymidine phosphorylase (TP), cause mitochondrial neurogastrointestinal encephalomyopathy (MNGIE)." (PMID 36513735, 2023). "Biallelic TYMP variants are responsible for Mitochondrial NeuroGastroIntestinal Encephalomyopathy (MNGIE), an autosomal recessive disorder characterized in most patients by gastrointestinal and neurological symptoms, ultimately leading to death." (PMID 35341481, 2022). "A number of TYMP loss-of-function mutations have previously been implicated in Mitochondrial NeuroGastroIntestinal Encephalomyopathy (MNGIE; MIM #603041), a rare metabolic autosomal recessive disease." (PMID 35341481, 2022). "Defects in TYMP, encoding thymidine phosphorylase (TP) are rare and cause a specific syndrome, mitochondrial neurogastrointestinal encephalomyopathy (MNGIE)." (PMID 35203288, 2022). "Mutations in the HsTP gene (TYMP) which result in either partial or complete loss of enzymatic activity, cause mitochondrial neurogastrointestinal encephalomyopathy (MNGIE) which is an autosomal recessive disease." (PMID 34976980, 2021). "For example, non-human mammals likely possess a UPP1 enzyme with a broader substrate specificity, which may have permitted the loss of the mitochondrial neurogastrointestinal encephalopathy-causing gene TYMP in six mammalian lineages by making it functionally redundant." (PMID 33575564, 2020). "Mitochondrial neurogastrointestinal encephalomyopathy (MNGIE) is an ultra-rare disorder caused by mutations in TYMP, leading to a deficiency in thymidine phosphorylase and a subsequent systemic accumulation of thymidine and 2’-deoxyuridine." (PMID 32183169, 2020).
mitochondrial neurogastrointestinal encephalomyopathy (continued). "Mitochondrial neurogastrointestinal encephalomyopathy (MNGIE) is an autosomal recessive disorder associated with deficiency of thymidine phosphorylase (TP)." (PMID 26124966, 2015). "Inactivating mutations in the gene encoding thymidine phosphorylase, TYMP, causes mitochondrial neurogastrointestinal encephalomyopathy (MNGIE), which is characterised by mtDNA mutation and depletion in patients." (PMID 40824221, 2025). "Mitochondrial neurogastrointestinal encephalomyopathy (MNGIE) is a rare autosomal recessive disorder caused by mutations in the TYMP gene, resulting in the loss of TYMP function." (PMID 40303404, 2025). "Similarly, the thymidine phosphorylase knockout mouse, associated with mitochondrial neurogastrointestinal encephalomyopathy (MNGIE) disease characterized by depletion and multiple deletions, does not accumulate mtDNA deletions." (PMID 40404629, 2025). "Mitochondrial Neurogastrointestinal Encephalomyopathy (MNGIE) is a very rare autosomal recessive disorder of nucleotide metabolism, caused by mutations of the TYMP gene, which codes for the thymidine phosphorylase (TP) enzyme, expressed in most human tissues." (PMID 39758336, 2025). "Lastly, the neurogastrointestinal MTDPS is notable for its effects on the brain and gastrointestinal tract, also known as the mitochondrial neurogastrointestinal encephalomyopathy (MNGIE) and mainly caused by the mutations of the TYMP gene." (PMID 40556660, 2025). "Mitochondrial neurogastrointestinal encephalopathy (MNGIE) is a rare autosomal recessive disorder caused by variants in the TYMP gene, which encodes thymidine phosphorylase (TP)." (PMID 40826089, 2025). "Two examples include the encapsulation of asparaginase and thymidine phosphorylase, which are proposed for pancreatic cancer and mitochondrial neurogastrointestinal encephalomyopathy patients, respectively." (PMID 38270470, 2024). "Mitochondrial neurogastrointestinal encephalopathy (MNGIE) syndrome is a rare autosomal recessive MD, caused by mutation in TYMP, the nuclear gene encoding the enzyme thymidine phosphorylase (TP)." (PMID 36471396, 2022). "Mitochondrial neurogastrointestinal encephalomyopathy (MNGIE) is a very rare autosomal recessive disease, caused by thymidine phosphorylase (TP) deficiency and TYMP mutations, which usually leads to death in early adulthood." (PMID 33802970, 2021). "Additionally, erythrocytes are being used in mitochondrial neurogastrointestinal encephalomyopathy (MNGIE) to compensate for the deficiency in thymidine phosphorylase by delivering the enzyme." (PMID 34502086, 2021). "A device developed by EdyDel was also used to prepare thymidine phosphorylase in erythrocytes (EE-TP) for the treatment of mitochondrial neurogastrointestinal encephalomyopathy." (PMID 32197542, 2020). "It is interesting to mention the mitochondrial neurogastrointestinal encephalomyopathy (MNGIE), which is a rare multisystemic autosomal recessive disorder caused by TYMP mutations." (PMID 32887417, 2020). "Mitochondrial neurogastrointestinal encephalomyopathy (MNGIE) is an ultra-rare autosomal recessive disorder of nucleoside metabolism that is caused by mutations in the nuclear thymidine phosphorylase gene (TYMP) gene, encoding for the enzyme thymidine phosphorylase." (PMID 30959750, 2019). "Mitochondrial neurogastrointestinal encephalomyopathy (MNGIE) is an ultra-rare metabolic autosomal recessive disease, caused by mutations in the nuclear gene TYMP which encodes the enzyme thymidine phosphorylase." (PMID 30627136, 2018). "The first such factor, thymidine phosphorylase (TP), was causally linked to mtDNA abnormalities and a specific mitochondrial disease, MNGIE (mitochondrial neurogastrointestinal encephalomyopathy) in 1999." (PMID 26760297, 2016). "MNGIE (mitochondrial neurogastrointestinal encephalomyopathy) is caused by mutations in the gene TYMP, encoding the enzyme thymidine phosphorylase." (PMID 24896153, 2015).
mitochondrial neurogastrointestinal encephalomyopathy (continued). "This is exemplified by mitochondrial neurogastrointestinal encephalomyopathy (MNGIE), which arises from a nucleotide imbalance caused by mutation of nDNA-encoded enzyme thymidine phosphorylase (TP) that is imported into mitochondria." (PMID 23547827, 2013). "Mitochondrial neurogastrointestinal encephalomyopathy (MNGIE-MTDPS1) is a devastating autosomal recessive disorder due to mutations in TYMP, which cause a loss of function of thymidine phosphorylase (TP), nucleoside accumulation in plasma and tissues, and mitochondrial dysfunction." (PMID 30373120, 2018). "In contrast, quantitative real-time PCR and 3’-RACE-RFLP analysis revealed unreduced nonstop mRNA levels in the patient with mitochondrial neurogastrointestinal encephalomyopathy harboring a nonstop mRNA mutation (c.1416delC) in the TYMP gene." (PMID 26892242, 2016). "Targeted deletion of thymidine phosphorylase (TP) in mice was hypothesized to give rise to an increase in plasma levels of thymidine and the disease pathologies associated with mitochondrial neurogastrointestinal encephalomyopathy (MNGIE)." (PMID 25923076, 2015). "Mitochondrial neurogastrointestinal encephalomyopathy (MNGIE) is a progressive and fatal autosomal recessive disorder caused by pathological mutations in the nuclear TYMP gene encoding the cytosolic enzyme, thymidine phosphorylase." (PMID 41009664, 2025). "Mitochondrial neurogastrointestinal encephalomyopathy (MNGIE) is an ultra-rare disease caused by mutations in TYMP, the gene encoding for the enzyme thymidine phosphorylase." (PMID 32914088, 2020). "Here, we will review two peculiar mitochondrial disorders, ethylmalonic encephalopathy (EE) and mitochondrial neurogastrointestinal encephalomyopathy (MNGIE), caused by mutations in the ETHE1 and TYMP nuclear genes, respectively." (PMID 26194912, 2015). "Mitochondrial neurogastrointestinal encephalomyopathy (MNGIE) is a severe human disease caused by mutations in TYMP, the gene encoding thymidine phosphorylase (TP)." (PMID 21483760, 2011). "Mitochondrial neurogastrointestinal encephalomyopathy (MNGIE) is a rare mitochondrial disease, reported in about 100 cases, which arises in patients carrying a recessive mutation in the TYMP gene, causing a deficiency in thymidine phosphorylase." (PMID 24499129, 2013). "Mitochondrial neurogastrointestinal encephalomyopathy (MNGIE, Online Mendelian inheritance in Man #603041, Genome Database accession #9835128) is an ultra-rare autosomal recessive disease caused by mutations in TYMP, the nuclear gene which encodes for the enzyme, thymidine phosphorylase." (PMID 33916195, 2021).